PORCN (porcupine O-acyltransferase)
Diseases named in the same sentence as PORCN in open-access papers (continued):
Sharing a sentence is not in itself a finding about the gene and the disease.
tumor (35 papers, 2012 to 2026). "In another study, the PORCN inhibitor ETC-1922159 has demonstrated potential in causing tumor necrosis by disrupting tumor angiogenesis." (PMID 38816668, 2024). "We also provide an overview of the clinical findings on GGS patients already reported and discuss the possible pathogenetic mechanism that may underlie this rare condition, including the role of PORCN in tumor susceptibility." (PMID 37859990, 2023). "We further examined if simultaneous administration of a clinically approved anti-resorptive, alendronate, could mitigate loss-of-bone mass and extend the beneficial anti-tumor effects of PORCN inhibitors to a larger number of human patients." (PMID 29844946, 2018). "For instance, porcupine o-acyltransferase (PORCN) inhibitors under development for oncology reduce tumor growth but also impair bone integrity, lowering bone mineral density and increasing fracture risk through Wnt pathway inhibition." (PMID 41282593, 2025). "Combination of the PORCN inhibitor ETC-159 with the PD-1 inhibitor nivolumab reduced tumor volume in mice engrafted with MSS CRC." (PMID 38280119, 2024). "Among these DEGs several genes with oncogenic and/or metastasis promoting function (e.g. STC1, YES1, PORCN) were found to be down-regulated and certain tumour suppressor genes (e.g. DKK1, PERP) showed overexpression in LINC00152-silenced cells." (PMID 32307642, 2020). "Starting on day 28 post-tumor challenge, mice were treated orally with the PORCN inhibitor CGX1321 daily for 14 days." (PMID 32213921, 2020). "Most importantly, as NOTUM is a secreted protein and its levels in blood correlate with tumor growth, it has potential as a pharmacodynamic biomarker for PORCN and other Wnt pathway inhibitors." (PMID 26848981, 2016). "In vivo studies of those PORCN inhibitors have shown significant tumor growth regression with evident downregulation of Wnt target genes." (PMID 27570510, 2016). "Recent studies demonstrate that Wnt or PORCN inhibitor, Wnt-C59, inhibits tumor growth in MMTV-WNT1 transgenic mice." (PMID 25980501, 2015). "Using several NPC cell lines, we now demonstrate that a PORCN inhibitor is able to inhibit Wnt signaling activities, arrest stemness properties, and suppress tumor cell growth in animal assays." (PMID 25980501, 2015). "This appeared to be dose dependent, as shP1 produced both a greater knockdown of PORCN and a greater reduction in tumor growth." (PMID 22509316, 2012). "Delay in tumor formation suggested that PORCN gene function is important to tumor take and/or progression and encouraged us to pursue a stable knockdown approach." (PMID 22509316, 2012). "MDA-MB-231 cells with transient PORCN knockdown displayed a 2-week delay in tumor take compared to controls." (PMID 22509316, 2012). "Since many PORCN inhibitors are in clinical trials for solid tumours with active Wnt signalling and radiotherapy is a major treatment option for such tumours, it is likely that PORCN inhibitors would exert beneficial effects in these patients when used concurrently with radiotherapy." (PMID 39497152, 2024). "Similarly to vector xenografts, PORCN-ΔNLS xenografts showed significantly more IR-induced tumour growth delay than PORCN-WT xenografts." (PMID 39497152, 2024). "Finally, treatment with the PORCN inhibitor significantly suppressed RNF43‐mutant cell‐derived PDX tumor development." (PMID 35040131, 2022). "However, combinatorial treatment with daily dosing of PORCN inhibitor LGK drastically reduced C4O tumor growth." (PMID 34367990, 2021). "As a result of this work, AXIN2 hypermethylation/silencing is proposed as a tractable biomarker of ligand-dependent tumours that may help prospectively stratify patients for therapies perturbing Wnt-pathway ligands, including PORCN inhibitors." (PMID 33673710, 2021). "In many other tumors, inhibition of PORCN has a good tumor-suppressing effect." (PMID 32104684, 2020).
tumor (continued). "Small changes in PORCN activity can induce significant inhibitory effects in rodent tumor models." (PMID 25980501, 2015). "However, the PORCN inhibitory approach is only suitable for a limited number of tumor cell lines having aberrant Wnt activation." (PMID 25980501, 2015). "To address whether PORCN knockdown might slow the growth of tumor cells in a more complex environment where additional stroma-derived signals can also stimulate proliferation, we investigated the rate of establishment of tumors in vivo." (PMID 22509316, 2012). "Interestingly, PORCN was expressed in a large percentage of SCGB1A1 tumor cells, too." (PMID 34249925, 2021). "Therefore, it is hypothesized that PORCN inhibitors are safe and effective in targeting tumor cells with excessive Wnt secretion compared to normal cells." (PMID 27570510, 2016). "LGK974, or WNT974, is an orally available small molecule PORCN inhibitor that decreases EOC cell viability in vitro and blocks tumor growth in vivo." (PMID 32560059, 2020). "In conclusion, the PORCN inhibitor WNT974 and the β-catenin inhibitor PRI-724 exert antiproliferative activities in human NET tumor cell lines in vitro." (PMID 32033025, 2020). "Several recent studies provide evidence showing that PORCN inhibitors, including Wnt-C59 and LGK974, inhibit or delay tumor growth in mouse models." (PMID 25980501, 2015). "CSCs are PORCN+ and provide WNT within their niches for tumor progressive purposes." (PMID 38280119, 2024). "In both studies, no patient showed a response to PORCN inhibitor therapy in terms of tumor reduction, and their clinical potential and tumor entities to be targeted remain an open question." (PMID 36982422, 2023). "Finally, PORCN inhibition significantly suppressed PDX tumor development of RNF43‐mutant CRC cells, suggesting that PORCN inhibitors are an effective therapeutic strategy against RNF43‐mutant CRC development and metastasis." (PMID 35040131, 2022). "Since cell line-derived spheroids lacked PORCN expression, we next isolated tumor organoids from patients according to previous methods." (PMID 34249925, 2021). "Moreover, PORCN inhibitors and anti-LRP5/6 antibodies have shown promising efficacy in preclinical models of Wnt-addicted tumours." (PMID 33673710, 2021). "However, the antitumor effect produced by inhibiting PORCN is not obvious in some tumors and even produces a tumor-promoting effect." (PMID 32104684, 2020). "Finally, we examined whether or not a PORCN inhibitor suppresses the tumor development of RNF43 frameshift mutant cells in PDX models." (PMID 35040131, 2022). "In summary, simultaneous, rather than sequential, treatment with chemotherapy and PORCN inhibitors reduced diapause-like WNTHigh enrichment in vitro and significantly enhanced TNBC tumor sensitivity to chemotherapy in vivo." (PMID 41117706, 2026). "Additionally, the expression levels of TGFB and PORCN also showed positive correlation with CD36 expression, suggesting that the TGF-β and Wnt/β-catenin signaling pathways may be the drivers of EMT program activation in the tumor samples with elevated CD36 levels." (PMID 26424075, 2015). "Therefore, many human tumor cells may not have responded to PORCN treatment because of the inappropriate or overexpressed levels of Wnt pathway activities or the involvement of other interacting pathways induced by aberrant Wnt signalling and accumulated mutations in these cells." (PMID 25980501, 2015). "The effects of PORCN NLS in the DDR were verified by colony formation assays, MTT assays, the DR/EJ5 homologous recombination/non-homologous end-joining reporter system, xenograft tumor growth and immunofluorescence." (PMID 39497152, 2024). "Importantly, similarly to what was seen in EP300 knockouts, ETC-159 treatment only minimally slowed down the GATA6-knockout tumor growth without reaching statistical significance, confirming that downregulating GATA6 conferred resistance to PORCN inhibition." (PMID 35536676, 2022).
genodermatosis (1 paper, 2025). "This genodermatosis is caused by a mutated PORCN gene, which encodes porcupine o-acyltransferase and results in abnormal ectodermal tissue development." (PMID 40276731, 2025).
neurological diseases (1 paper, 2021). "Our results increase the possibility that a specific PORCN inhibitor contributes to regulating the Wnt pathway so that it become a safe and plausible methodology for cell replacement therapy in neurological diseases." (PMID 34399774, 2021).
PORCN also shares sentences with these, for which no sentence is quoted: head and neck squamous cell carcinoma (3 papers); papilloma (2); angioma serpiginosum (1); cervical cancer (1); cystic fibrosis (1); epilepsy (1); glioblastoma (1); ichthyosis (1); lymphoblastic leukemia (1); microcephaly (1); neuroendocrine tumor (1); Obesity (1); osteoporosis (1); osteosarcoma (1); pancreatic ductal adenocarcinoma (1); periodontitis (1).